MIR4475 (microRNA 4475)
Synonyms: hsa-mir-4475
Gene: MicroRNA gene on chromosome 9 (36,823,539 to 36,823,599, reverse strand). Ensembl gene ENSG00000266255.
Homologues: Orthologues: chimpanzee MIR4475 (100% identical).